CRP (C-reactive protein)
Diseases named in the same sentence as CRP in open-access papers (continued):
Sharing a sentence is not in itself a finding about the gene and the disease.
metastatic melanoma (17 papers, 1994 to 2025). A melanoma that has spread from its primary site to another anatomic site. "In past large randomized trials, higher IL-6 and CRP were associated with shorter overall survival in patients with metastatic melanoma who received ICI or chemotherapy." (PMID 38952546, 2024). "C-reactive protein was introduced in this study as elevated levels in serum have been associated with shortened survival in metastatic melanoma patients and resistance to interleukin-2 therapy." (PMID 15280926, 2004). "Moreover pre-treatment CRP levels have been associated with poor survival in patients with metastatic melanoma who are undergoing ICI therapy." (PMID 40091005, 2025). "CRP appeared particularly elevated in pancreatic adenocarcinoma cells, exceeding the concentration detected in metastatic melanoma and healthy control skin by over 24-fold." (PMID 38698774, 2024). "On the other hand, recent findings showed that elevated levels of CRP impaired adaptive immunity and propagated immunosuppression in patients with metastatic melanoma." (PMID 37603206, 2023). "The elevation of CRP levels has been reported as a poor predictor of advanced UCs and metastatic melanoma treated with ICIs." (PMID 34757531, 2022). "CRP levels were found in primary (1.07 ± 0.88 ng/ml) and metastatic melanoma (1.85 ± 0.62 ng/ml) significantly higher when compared with the control group (0.12 ± 0.12 ng/ml)." (PMID 32855975, 2020). "Loss of mid-arm muscle was linked to CRP among patients with NSCLC and metastatic melanoma, suggesting that loss of peripheral muscle mass at this site was linked to the inflammatory response." (PMID 15726121, 2005). "Interleukin 6 and C-reactive protein (CRP) were determined prior to IL-2 therapy in sera from metastatic melanoma patients." (PMID 8180022, 1994). "Additionally, some reports have suggested an association between clinical parameters, such as lactate dehydrogenase (LDH) and C-reactive protein (CRP), and the efficacy of immune checkpoint inhibitor in metastatic melanoma patients." (PMID 29262550, 2017). "Another study comparing several laboratory and clinical factors in metastatic melanoma reported that albumin was an independent predictor for immunotherapy response after adjustment for LDH, CRP, NLR, brain metastasis, sex, and age41,42." (PMID 38755213, 2024). "High baseline serum LDH and CRP levels, a high NLR and a poor PS have been reported as prognostic factors for poor survival in patients with metastatic melanoma." (PMID 34115870, 2021). "CRP and NLR have been studied as a prognostic biomarker of nivolumab in several cancers including NSCLC, metastatic renal cell carcinoma, metastatic melanoma, and R/M HNSCC." (PMID 32824226, 2020). "IL-8 and CRP had no statistically significant variation when compared to primary versus metastatic melanoma groups." (PMID 32855975, 2020). "Among patients with metastatic melanoma, there was a negative correlation between mean CRP and change in MAMC (Rs −0.617; P<0.05)." (PMID 15726121, 2005).
Mitral regurgitation (17 papers, 2009 to 2025). An abnormality of the mitral valve characterized by insufficiency or incompetence of the mitral valve resulting in retrograde leaking of blood through the mitral valve upon ventricular contraction. "Each increase of 1 unit of CRP was associated with increased odds of having mitral regurgitation by 1.005 times (95% C.I.: 1.001–1.009)." (PMID 38256299, 2023). "Anterior MI, Killip class ≥2, number of pathological Q leads (at discharge), ST segment deviation score (at admission and discharge), C-reactive protein (CRP), end-diastolic volume, and mitral regurgitation were found to have a significant positive correlation with thrombus." (PMID 38222227, 2023). "CRP, triglycerides, HDL-cholesterol, and secondary ST-T changes were significantly different between groups in patients with mitral regurgitation." (PMID 38256299, 2023). "In the case of mitral regurgitation, in univariate models, HDL-cholesterol was not a significant predictor (p = 0.055), while CRP (p = 0.019), triglycerides dyslipidemia (p = 0.043) and secondary ST-T changes (p = 0.024) were significant predictors." (PMID 38256299, 2023).
pneumococcal pneumonia (17 papers, 2005 to 2024). A febrile disease caused by STREPTOCOCCUS PNEUMONIAE. "A previous study that compared IPD and pneumococcal pneumonia showed that a CRP level ≥ 17.0 mg/dL was a useful factor for suspicion of IPD." (PMID 38898407, 2024). "C-reactive protein (CRP) was discovered in 1930 in the sera of patients during the acute phase of pneumococcal pneumonia and was so named because it bound to the C-polysaccharide of the pneumococcal cell wall." (PMID 36936978, 2023). "Crackles were associated with abnormal chest radiography using both digital and conventional auscultation, and were found more frequently in children with high CRP and likely pneumococcal pneumonia." (PMID 35577452, 2022). "C-reactive protein (CRP) was discovered during the seminal studies of pneumococcal pneumonia being performed in the laboratory of Oswald T. Avery (1877-1955)." (PMID 33633738, 2020). "We therefore believe that class of children with NP carriage of serotype 1 and high CRP as pneumococcal pneumonia has biological relevance, and internal and external validity." (PMID 32039044, 2019). "High CRP levels have also been noticed in patients with bacteremia following pneumococcal pneumonia." (PMID 20011658, 2009). "For example, C-reactive protein elevates during the acute phase of pneumococcal pneumonia." (PMID 32983729, 2020). "Long ago, CRP was initially discovered as a test for patients with pneumococcal pneumonia." (PMID 19594893, 2009). "In our cohort, none of the individuals who had a positive SpUA had an elevated CRP, suggesting that most of these children did not have pneumococcal pneumonia and were instead colonized." (PMID 34817224, 2021). "None of those who tested positive also had a CRP of >80 mg/L, the combination of which has been shown to be predictive of pneumococcal pneumonia." (PMID 34817224, 2021). "C-reactive protein and procalcitonin improve the specificity of CXR to diagnose pneumococcal pneumonia and may be useful for the future evaluation of the effectiveness of pneumococcal conjugate vaccine in preventing pneumococcal pneumonia." (PMID 15736995, 2005).
scleroderma (17 papers, 2013 to 2025). Scleroderma is a rare autoimmune connective tissue disorder characterized by abnormal hardening of the skin and, sometimes, other organs. "Scleroderma patients may have an elevated serum CRP level compared to healthy controls, which has also been confirmed in our present study." (PMID 39857802, 2025). "Moreover, increased CRP levels were determined in the scleroderma group (2.7 vs. 5.04 mg/L; p < 0.05)." (PMID 39000486, 2024). "In outpatient clinic conditions, C-reactive protein remains nonspecific and specific methods such as the European Scleroderma Trials and Research group take a long time." (PMID 41342238, 2025). "All other rheumatologic and infectious workups were negative, including HIV, ACE, ANA, ANCA, CRP, anti-scleroderma antibody and HCV." (PMID 40038144, 2025). "In contrast, in patients with scleroderma, the serum CRP levels showed a significant negative correlation with time-based heart rate variability (HRV) (r = −0.24; p < 0.05)." (PMID 39000486, 2024). "However, CRP monitoring is of little value in measuring disease activity in SLE, scleroderma, polymyositis, or dermatomyositis where CRP levels do not correlate well with disease activity." (PMID 24167754, 2013).
soft tissue sarcoma (17 papers, 2014 to 2025). A malignant neoplasm arising from muscle tissue, adipose tissue, blood vessels, fibrous tissue, or other supportive tissues excluding the bones. "In soft tissue sarcomas, CRP levels were associated with the degree of tumor infiltration determined by magnetic resonance imaging (MRI) as well as disease-specific survival." (PMID 33324413, 2020). "Study by Nakamura in 2013 involving 332 adult patients with primary soft tissue sarcoma showed that CRP values were significantly associated with oncological outcomes and patient survival." (PMID 32884743, 2020). "There were significant associations between the tumor growth pattern and CRP levels in patients with high-grade soft-tissue sarcoma." (PMID 28727824, 2017). "We also found that univariate and multivariate analyses showed that the MRI growth pattern and elevated CRP were associated with disease-specific and metastasis-free survivals in patients with high-grade soft-tissue sarcoma." (PMID 28727824, 2017). "With similarity of the role of CRP in other malignancies, elevated level of CRP is also associated with poor prognosis of soft-tissue sarcoma patients." (PMID 24800842, 2014). "Additionally, an association between serum CRP level and tumor diagnosis in this study can be explained by the state of inflammation in the soft tissue sarcoma." (PMID 32183216, 2020). "Among others, both preoperative levels of neutrophils, in the form of NLR, and CRP have been investigated as prognostic factors in several types of cancer including soft tissue sarcoma." (PMID 40025678, 2025). "CRP is the only single biomarker that, according to the literature, is prognostic of both bone and soft tissue sarcomas as well as for cancer." (PMID 36900365, 2023). "Further investigation is required to confirm the correlation of CRP levels and PD-L1 expression levels in soft tissue sarcomas." (PMID 31260491, 2019). "We hypothesized that lymphocyte to C-reactive protein ratio (LCR) could predict survival in 132 patients with soft tissue sarcoma (STS)." (PMID 36358634, 2022). "Elevated CRP levels might represent high level of PD-L1 expression in malignancies including soft tissue sarcomas, thus CRP might have a role to serve as an indicator for immune checkpoint blockade therapy with anti-PD-1 antibodies." (PMID 31260491, 2019). "The aim of this study was to evaluate whether pretreatment serum CRP level could serve as a reliable independent prognostic indicator for survival in patients with soft tissue sarcoma (STS)." (PMID 31260491, 2019). "Data on individual co-morbidities may not be completely captured and other inflammatory markers known to be prognostic in soft tissue sarcoma, such as CRP, ESR or albumin were also unavailable." (PMID 30097600, 2018). "Univariate analysis of the diagnosis of soft tissue sarcoma and clinical characteristics or laboratory data revealed a significant association between diagnosis and age (p < 0.001), tumor size (p < 0.001), WBC count (p < 0.001), Hb count (p < 0.001), CRP level (p < 0.001), and LDH level (p < 0.001)." (PMID 32183216, 2020). "The aim of this study was to determine whether the tumor infiltrative growth pattern on magnetic resonance imaging (MRI) was associated with blood inflammatory markers (C-reactive protein; CRP and Neutrophil-lymphocyte ratio; NLR) and survival in patients with high-grade soft-tissue sarcoma (STS)." (PMID 28727824, 2017). "We confirmed that high WBC count, low Hb count, high serum CRP level, and high serum LDH level were independent predictive factors for soft tissue sarcoma using multivariate analysis." (PMID 32183216, 2020). "They reported that age, duration of symptoms, tumor size, serum C-reactive protein (CRP) level, and comorbidity are prognostic factors for soft tissue sarcomas." (PMID 32183216, 2020). "Older patients with large tumors, high WBC count, low Hb count, high serum CRP level, and high serum LDH level were likely to be diagnosed with soft tissue sarcoma." (PMID 32183216, 2020).
soft tissue sarcoma (continued). "The prognostic value of CRP has also been evaluated in patients affected by bone and soft tissue sarcomas, without differentiating the various histotypes that have distinct treatments and prognoses." (PMID 36900365, 2023).
Takayasu arteritis (17 papers, 2009 to 2024). A rare inflammatory large-vessel vasculitis primarily affecting the aorta and its major branches, but also other large vessels, causing stenosis, occlusion, or aneurysm. "In a recent retrospective study on 32 patients with Takayasu’s arteritis and 32 healthy controls, the CAR was significantly associated with disease activity, CRP, and ESR." (PMID 35505647, 2022). "The CRP/Alb ratio also was higher in patients with active Takayasu arteritis than patients in remission (11.26 vs. 1.34, p < 0.001)." (PMID 33324592, 2020). "In one recent report, patients with Takayasu arteritis had a much higher CRP/Alb ratio than healthy controls (13.20 vs. 0.73, p < 0.001)." (PMID 33324592, 2020). "One recent study has demonstrated that CRP/Alb ratio is a marker of disease activity in Takayasu arteritis." (PMID 33324592, 2020). "C-reactive protein/albumin ratio and red blood cell distribution width can be used in the diagnosis of Takayasu arteritis, and C-reactive protein/albumin ratio, red blood cell distribution width, and monocyte/HDL ratio measurements can be used in the follow-up." (PMID 38775535, 2024). "Currently, the major way of monitoring Takayasu arteritis is based on the evaluation of conventional inflammation biomarkers, including serum erythrocyte sedimentation rate (ESR), C-reactive protein (CRP) level, and the imaging tests, such as angiography." (PMID 35596814, 2022). "A characteristic laboratory feature for childhood Takayasu arteritis that did not occur in our patient is elevated acute phase reactants: ESR or CRP." (PMID 32239321, 2020). "First, we excluded Takayasu arteritis because there was no sign of fever and a C-reactive protein level within normal limits." (PMID 24384893, 2015). "We verified whether the blood concentrations of PTX3 and of C-reactive protein (CRP) in patients with Takayasu arteritis (TA) might reflect vascular wall involvement, as assessed by signal enhancement after contrast media administration, and the progression of arterial involvement." (PMID 25394473, 2014). "The patient did not have any features that suggest Takayasu's arteritis, such as night sweats, fatigue, arthralgias, weight loss, pulseless arteries in arms or legs, or elevated ESR or CRP." (PMID 25104961, 2014). "Whether the circulating levels of pentraxin 3 (PTX3), an acute phase reactant (APR), are higher in active Takayasu arteritis (TAK), and if so, whether PTX3 is more accurate than C-reactive protein (CRP) in TAK activity assessment has been investigated in this study." (PMID 33529185, 2021).
acute cholangitis (16 papers, 2013 to 2026). Cholangitis that is both sudden in onset and of a relatively short duration. "Variables such as age, poor PS, WBC, CRP, acute cholangitis, hospital stay before surgery, and blood loss in the A + B + C and (A or B) + C groups were higher than those in the other groups." (PMID 27239193, 2016). "Surprisingly, shortly before and after ERCP, OCBD subjects presented with lower alanine aminotransferase levels; however, they had higher C-reactive protein levels, suggesting a higher susceptibility to development of acute cholangitis." (PMID 23365676, 2013). "Laboratory studies showed leukocytosis with neutrophilia, markedly elevated transaminases, cholestatic enzyme elevation, hyperbilirubinemia, and elevated CRP, consistent with acute cholangitis." (PMID 41246620, 2025). "According to TG18, patients with simultaneous elevation of CRP and hepatobiliary enzymes are diagnosed with acute cholangitis." (PMID 39594255, 2024). "The area under the curve (AUC) for the NLR, WBC, and CRP for severe acute cholangitis was 0.87, 0.73, and 0.74, respectively." (PMID 35208579, 2022). "The optimal cut-off values of the NLR, WBC and CRP for predicting severe acute cholangitis were 15.24 (sensitivity, 85%; specificity, 79%), 11,150 (sensitivity, 71%; specificity, 68%), and 7.18 (sensitivity, 67%; specificity, 66%), respectively." (PMID 35208579, 2022). "It has been reported that acute suppurative cholangitis (ASC), the severe form of acute cholangitis, is associated with abnormal WBC and high CRP level." (PMID 32508526, 2020). "In contrast, 59.5% of our study population suffered already at the time of ERC from acute cholangitis (defined as bacterial colonization of the biliary system and elevated leucocytes > 12 000/μl/CRP > 5 mg/l)." (PMID 28086796, 2017). "Signs of acute cholangitis including fever, epigastric pain, or an elevated serum C-reactive protein, were observed in 22 patients." (PMID 25234181, 2014). "In the context of limited evidence from Eastern European populations, this study aimed to compare the performance of NLR and CRP in identifying organ dysfunction-based severe presentation of acute cholangitis according to a modified TG18-derived classification." (PMID 42195068, 2026). "For example, in one study, right upper quadrant pain, fever, leukocyte count > 12,000/μL, and CRP > 3 mg/L, ALT, and total bilirubin > ULN were considered acute cholangitis." (PMID 36161594, 2022). "Regarding the inflammatory markers, the severe acute cholangitis group had significantly higher WBC (15,600 vs. 9655, p < 0.001), CRP (10.15 vs. 4.68, p = 0.001) and NLR (22.27 vs. 8.07, p < 0.001) than the mild/moderate acute cholangitis group." (PMID 35208579, 2022). "In the ROC analysis, the NLR could discriminate severe acute cholangitis (AUC 0.87), shock (0.81), and positive blood culture (0.76) better than WBC or CRP." (PMID 35208579, 2022). "Similarly, another Japanese study of 213 patients reported that the AUC for procalcitonin in predicting severe acute cholangitis was 0.9, which was significantly higher than those of WBC (0.62) and CRP (0.7)." (PMID 35208579, 2022). "We found that suPAR levels correlate with CRP levels in patients with PSC and that suPAR levels can indicate the presence of acute cholangitis episodes, which is consistent with previous findings suggesting the involvement of suPAR in systemic inflammatory responses." (PMID 35566603, 2022). "Although all three markers were predictive for severe acute cholangitis (p < 0.001 for all), the AUC of the NLR in predicting severe acute cholangitis was 0.87 (95% CI, 0.82–0.92), which was higher than that of the WBC count (0.73 (95% CI, 0.6–0.86)) and the CRP level (0.74 (95% CI, 0.65–0.84))." (PMID 35208579, 2022). "The ROC curves showed that the NLR was predictive for severe acute cholangitis (p = 0.001), but WBC and CRP were not (p = 0.126 and p = 0.069, respectively)." (PMID 35208579, 2022).